RAB11A (RAB11A, member RAS oncogene family)
Description:
The small GTPases Rab are key regulators of intracellular membrane trafficking, from the formation of transport vesicles to their fusion with membranes. Rabs cycle between an inactive GDP-bound form and an active GTP-bound form that is able to recruit to membranes different set of downstream effectors directly responsible for vesicle formation, movement, tethering and fusion. RAB11A regulates endocytic recycling. Forms a functional Rab11/RAB11FIP3/dynein complex that regulates the movement of peripheral sorting endosomes (SE) along microtubule tracks toward the microtubule organizing center/centrosome, generating the endosomal recycling compartment (ERC). Acts as a major regulator of membrane delivery during cytokinesis. Together with MYO5B and RAB8A participates in epithelial cell polarization. Together with Rabin8/RAB3IP, RAB8A, the exocyst complex, PARD3, PRKCI, ANXA2, CDC42 and DNMBP promotes transcytosis of PODXL to the apical membrane initiation sites (AMIS), apical surface formation and lumenogenesis. Together with MYO5B participates in CFTR trafficking to the plasma membrane and TF (Transferrin) recycling in nonpolarized cells. Required in a complex with MYO5B and RAB11FIP2 for the transport of NPC1L1 to the plasma membrane. Participates in the sorting and basolateral transport of CDH1 from the Golgi apparatus to the plasma membrane. Regulates the recycling of FCGRT (receptor of Fc region of monomeric IgG) to basolateral membranes (By similarity). May also play a role in melanosome transport and release from melanocytes (By similarity). Promotes Rabin8/RAB3IP preciliary vesicular trafficking to mother centriole by forming a ciliary targeting complex containing Rab11, ASAP1, Rabin8/RAB3IP, RAB11FIP3 and ARF4, thereby regulating ciliogenesis initiation. On the contrary, upon LPAR1 receptor signaling pathway activation, interaction with phosphorylated WDR44 prevents Rab11-RAB3IP-RAB11FIP3 complex formation and cilia growth. Participates in the export of a subset of neosynthesized proteins through a Rab8-Rab10-Rab11-endososomal dependent export route via interaction with WDR44. Also interacts with RABL3 to promote ciliary vesicle formation.
Synonyms: YL8
Tractability: Small molecule: a structure with a bound ligand is known; it has a high-quality binding pocket. Antibody: UniProt places it where antibodies can reach, with high confidence; its Gene Ontology location is reachable by antibodies, with medium confidence. PROTAC: ubiquitination databases record sites on it.
Target class: Enzyme; Hydrolase
Gene: Protein-coding gene on chromosome 15 (65,726,054 to 65,891,989, forward strand). Ensembl gene ENSG00000103769.
Subcellular location: Cell membrane; Endosome membrane; Recycling endosome membrane; Cleavage furrow; Cytoplasmic vesicle, phagosome membrane; Golgi apparatus membrane; Golgi apparatus, trans-Golgi network; Cytoplasmic vesicle membrane; Cell projection, cilium
Subcellular location (Human Protein Atlas): Centriolar satellite; Vesicles; Basal body; Cytosol; Equatorial segment; Mid piece; Primary cilium; Principal piece
Pathways (Reactome):
Organelle biogenesis and maintenance: Anchoring of the basal body to the plasma membrane; VxPx cargo-targeting to cilium
Vesicle-mediated transport: TBC/RABGAPs; Translocation of SLC2A4 (GLUT4) to the plasma membrane
Metabolism of proteins: RAB geranylgeranylation
Transport of small molecules: Vasopressin regulates renal water homeostasis via Aquaporins
Gene Ontology:
Molecular function: dynein light intermediate chain binding; G protein activity; GTPase activity; microtubule binding; myosin V binding; protein binding; syntaxin binding; GTP binding
Biological process: amyloid-beta clearance by transcytosis; astral microtubule organization; endocytic recycling; establishment of protein localization to membrane; establishment of protein localization to organelle; establishment of vesicle localization; exosomal secretion; mitotic metaphase chromosome alignment; mitotic spindle assembly; multivesicular body assembly; neuron projection development; positive regulation of epithelial cell migration; positive regulation of G2/M transition of mitotic cell cycle; positive regulation of mitotic cytokinetic process; protein localization to cilium; protein localization to plasma membrane; regulation of cilium assembly; regulation of cytokinesis; regulation of endocytic recycling; regulation of protein localization to centrosome; regulation of vesicle-mediated transport; vesicle-mediated transport; exocytosis; Golgi to plasma membrane protein transport; melanosome transport; and 7 more
Cellular component: centriolar satellite; centrosome; cilium; cleavage furrow; cytoplasmic vesicle; cytoplasmic vesicle membrane; endocytic vesicle membrane; endosome membrane; extracellular exosome; glutamatergic synapse; Golgi apparatus; Golgi membrane; kinetochore microtubule; multivesicular body; phagocytic vesicle; plasma membrane; postsynaptic recycling endosome; protein-containing complex; recycling endosome; recycling endosome membrane; spindle pole; trans-Golgi network; trans-Golgi network membrane; vesicle; cytosol; and 8 more
Genetic constraint (gnomAD): Loss-of-function variants: 8 observed, 25 expected, observed/expected ratio (o/e) 0.32, 90% interval 0.19 to 0.58. The upper end of that interval is the gene's LOEUF score, 0.58, which puts it in group 2 of 6, group 1 being the genes least tolerant of losing a copy. Missense variants: 96 observed, 251.05 expected, observed/expected ratio (o/e) 0.38, 90% interval 0.32 to 0.45. Synonymous variants: 73 observed, 80.46 expected, observed/expected ratio (o/e) 0.91, 90% interval 0.75 to 1.1.
Gene-disease validity (ClinGen):
ClinGen rates the evidence that RAB11A causes each of these diseases.
complex neurodevelopmental disorder with motor features (autosomal dominant): Moderate. A complex neurodevelopmental disorder that involves more than one phenotype associated with the central nervous system, including but not limited to intellectual disability, autism, and seizures (epilepsy).
Homologues: Orthologues: chimpanzee RAB11A (100% identical), dog RAB11A (100% identical), guinea pig RAB11A (100% identical), macaque RAB11A (100% identical), mouse Rab11a (100% identical), pig RAB11A (100% identical), rat Rab11a (100% identical), tropical clawed frog rab11a (98% identical), zebrafish rab11a (95% identical), Drosophila melanogaster Rab11 (85% identical), rabbit RAB11A (67% identical). Paralogues in human: RAB11B (91% identical), RAB25 (59% identical), RAB2B (46% identical), RAB2A (45% identical), RAB14 (44% identical), RAB1B (44% identical), RAB1A (44% identical), RAB4B (44% identical), RAB43 (43% identical), RAB4A (43% identical), RAB8B (43% identical), RAB8A (41% identical), and 56 more.
Diseases named in the same sentence as RAB11A in open-access papers:
RAB11A is named in the same sentence as 118 diseases in open-access papers, as found by Europe PMC text mining. Sharing a sentence is not in itself a finding about the gene and the disease. The quoted sentences say what the papers report.
breast carcinoma (24 papers, 2012 to 2026). "Up-regulation of Rab11 family members (Rab11A/11B/25) is associated with more aggressive prostate, ovarian, and breast cancers." (PMID 24492843, 2014). "In a study on breast cancer, RAB11A overexpression accelerated tumor cell viability, migration, and invasiveness." (PMID 40270615, 2025). "In a different cell type, BT20 breast cancer cells, knockdown of Rab4a, Rab4b, Rab11a, Rab11b or Rab25 significantly decreased motility, as did knockdown of CLINT1 or SH3BP5L." (PMID 37232246, 2023). "Previous data had shown RAB11A was upregulated in thyroid cancer, breast cancer, pancreatic cancer, and bladder cancer, suggesting the importance of RAB11A in human cancers’ development." (PMID 33292272, 2020). "In breast cancer cells, downregulation of Rab11A by tumor suppressor miRNA miR-320a and miR-452 inhibits breast cancer growth, motility and invasion." (PMID 29954076, 2018). "Previous reports indicate that Rab11a serves as a cancer biomarker in pancreatic and breast cancers." (PMID 28468127, 2017). "MiR-452, as a tumor-inhibitor of breast cancer, targets the RAB11A gene directly." (PMID 29715309, 2018). "Interestingly, Rab11a regulates EGFR circulation and promotes proliferation, but inhibits the movement in breast cancer." (PMID 34141705, 2021). "Further, brain metastases derived from multiple breast cancer cell lines showed more than 15 fold increase of Rab11b expression compared with cultured cells, with no change in Rab11a or Rab25 levels, suggesting the brain metastatic microenvironment specifically influences Rab11b expression." (PMID 32541798, 2020).
Huntington disease (15 papers, 2014 to 2025). Huntington disease (HD) is a rare neurodegenerative disorder of the central nervous system characterized by unwanted choreatic movements, behavioral and psychiatric disturbances and dementia. "Previous studies demonstrated that the deficiency of Rab11a was the pathogenesis of Huntington’s disease." (PMID 40437641, 2025).
viral infection (15 papers, 2013 to 2025). "Our results align with prior evidence highlighting the dependence of HPIV3 on RAB11A-associated endosomal trafficking, a phenomenon observed in various viral infections." (PMID 40259361, 2025). "Analysis of immunoprecipitated input by mass spectrometry confirms that the total levels of the dynein proteins are not altered during infection, suggesting that decreases in Rab11A and dynein association are specific to viral infection." (PMID 31911620, 2020). "The present review explores the roles of the ERC in viral infection, which have been linked to Rab11a and to a lesser extent to Rab11b and Rab25." (PMID 27005655, 2016). "Since WSN PA-GFP foci colocalize with PB2 vRNA segment it is likely that WSN PA-GFP and Rab11a also associate, suggesting that the dynamic colocalization events observed during viral infection might also involve Rab11a-containing recycling endosomes." (PMID 24603687, 2014). "The depletion of RAB11A prevents the formation of large cytoplasmic inclusions of vRNPs upon viral infection, as expected from previous studies, but does not affect the remodeling of CLIMP63+ membranes." (PMID 40668844, 2025). "Further studies examining Rab11A dynamics during infection with other RNA viruses that use Rab11A transport machinery, such as Sendai virus, will help further elucidate the conserved role of Rab11A during viral infection." (PMID 31911620, 2020). "To define which proteins were specifically enriched by the Rab11a IP versus those just increasing in abundance after viral infection, we normalized the abundance of each protein identified in IP by its abundance in the whole-cell lysate." (PMID 32843550, 2020). "Taken together, these data demonstrate that Rab11A movement is altered during viral infection by distinct RNA viruses, but that IAV can also utilize a microtubule-independent mechanism of vRNP intracellular transport." (PMID 31911620, 2020). "Based on these data, we predict an important role for Rab11A-RE in the transport and assembly of multiple RNA viruses that can be manipulated to interfere with viral infection." (PMID 31911620, 2020). "It is nevertheless an important result because it suggests a universal Rab11A-mediated transport pathway for influenza viral infections." (PMID 31911620, 2020). "Using these methods, we effectively quantified the impact of various treatments and virus infection on cellular transport of Rab11A and influenza vRNP." (PMID 31911620, 2020). "Recent studies have demonstrated a direct interaction between PB2 and Rab11A during a productive viral infection, solidifying the role of Rab11A RE during vRNP cytoplasmic transport." (PMID 28724771, 2017). "Thus, it is possible that these adaptor proteins are recruited to Rab11a-positive recycling endosomes upon virus infection, possibly through the JNK1 signaling pathway, to switch the destination of recycling endosomes from the plasma membrane to autophagosomes." (PMID 30619194, 2018).
colorectal cancer (12 papers, 2014 to 2025). A primary or metastatic malignant neoplasm that affects the colon or rectum. "Knocking down Rab7 in HCT116 colorectal cancer cells inhibits total exosomes release but promotes the secretion of Rab11a positive exosomes." (PMID 36320056, 2022). "Rab11a overexpression has been reported in non-small-cell lung cancer, pancreatic cancer, and colorectal carcinoma." (PMID 33178272, 2020). "Rab11a is upregulated, regulates in colorectal carcinoma, and inhibits E-cadherin expression, which induces cell transformation." (PMID 33178272, 2020). "Furthermore, CHMP5 knockdown in human HCT116 colorectal cancer cells selectively inhibits Rab11a‐exosome production." (PMID 36872252, 2023). "These vesicles, termed Rab11a‐exosomes, are preferentially secreted under nutrient stress from several cancer cell types, including HCT116 colorectal cancer (CRC) cells." (PMID 38887984, 2024). "To further investigate the specific properties of Rab11a‐exosomes, we isolated five paired preparations of sEVs from HCT116 colorectal cancer cells under glutamine‐depleted and glutamine‐replete conditions." (PMID 36872252, 2023).
prostate carcinoma (10 papers, 2020 to 2025). A carcinoma that arises from epithelial cells of the prostate gland. "PF562271 suppressed the malignant characteristics of prostate cancer cells caused by RAB11A knockdown." (PMID 36760469, 2023). "The possible mechanism of RAB11A promoting prostate cancer is associated with the activation of the FAK/AKT pathway." (PMID 36760469, 2023). "Thus, we hypothesized that the potential mechanism of RAB11A in prostate cancer might be associated with the FAK/AKT signaling pathway." (PMID 36760469, 2023). "In a prostate cancer study, RAB11A inhibition was found to attenuate cancer cell proliferation and invasiveness." (PMID 40270615, 2025). "Taken together, our data suggest that RAB11A, as an oncogenous protein, promotes prostate cancer malignant progression and tumorigenesis through activating FAK/AKT signaling." (PMID 36760469, 2023). "This study aimed to investigate the possible effect of RAB11A in prostate cancer and further explore the potential mechanisms." (PMID 36760469, 2023). "As another member of the Rab subfamily, RAB11A in the present study showed similar functions, facilitating the proliferation, migration, and invasion of prostate cancer." (PMID 36760469, 2023). "Results showed both the mRNA and protein expression of RAB11A were remarkably overexpressed in human prostate cancer cell lines (DU145, VCaP, and PC-3) compared with those in normal RWPE1 cells (P < 0.05)." (PMID 36760469, 2023). "Our data showed a similar effect of RAB11A overexpression in prostate cancer, promoting the proliferation, invasion, and migration of cancer cells." (PMID 36760469, 2023). "We first used RT-qPCR and western blot assays to measure the expression level of RAB11A in prostate cancer cells." (PMID 36760469, 2023). "In this work, we found that the RAB11A is upregulated in prostate cancer cells and promotes the progression of prostate cancer in vitro and in vivo through activating FAK/AKT signaling." (PMID 36760469, 2023). "RAB11A promotes cell malignant progression and tumor formation in prostate cancer via activating FAK/AKT signaling pathway." (PMID 36760469, 2023). "Meanwhile, the potential mechanism of RAB11A against prostate cancer was explored through in vitro and in vivo experiments to identify a novel potential target for the treatment of prostate cancer." (PMID 36760469, 2023). "In conclusion, the current study identified the role of RAB11A as a tumor promoter overexpressed in human prostate cancer." (PMID 36760469, 2023). "RAB11A involves the regulation of the Wnt/β-catenin pathway to promote the deterioration of prostate cancer, and RAB5A upregulation is related with the proliferation invasion and EMT of ovarian cancer." (PMID 36438897, 2022). "RAB11A knockdown decreased the prostate cancer cell proliferation, migration, and invasion." (PMID 36760469, 2023). "Therefore, the aim of the present study was to investigate the potential role of RAB11A in the development of prostate cancer." (PMID 36760469, 2023). "Therefore, we speculated that RAB11A promotes prostate cancer progression via the FAK/AKT pathway." (PMID 36760469, 2023). "However, the potential effects and mechanisms of RAB11A in prostate cancer remain unknown." (PMID 36760469, 2023). "Meanwhile, in vivo experiment showed that the interference of RAB11A reduced the tumor growth and downregulated the protein levels of p-FAK/FAK and p-AKT/AKT in tumor tissues of prostate cancer." (PMID 36760469, 2023). "The upregulation of recycling endosomes in prostate cancer (such as RAB4 and RAB11A) and altered trafficking and disrupted endosome biogenesis may enhance the transport of ADCs back to the plasma membrane and limit the delivery to the acidic compartments required to release the MMAE." (PMID 41303628, 2025).
Alzheimer disease (9 papers, 2014 to 2023). A progressive, neurodegenerative disease characterized by loss of function and death of nerve cells in several areas of the brain leading to loss of cognitive function such as memory and language. "Furthermore, Rab11A has been associated with neurodegenerative pathologies like Parkinson’s and Alzheimer’s diseases featuring as an important regulator for the trafficking of both alfa-synuclein or Aβ arising during the development of these diseases." (PMID 36995559, 2023).
cyst (9 papers, 2010 to 2021). A sac-like closed membranous structure that may be empty or contain fluid or amorphous material. "Together, our results show similar functional requirements of Rab3A, Rab8A, Rab11A and Rab27A compared to what has been previously reported using MDCK cyst models of epithelial lumen formation." (PMID 32569321, 2020). "As the WT cyst matured, EEA1/Vps35-labelled EE and Rab11a-labelled RE became spatially resolved in the apical cytoplasm." (PMID 26786190, 2016). "During the course of MDCK cyst maturation, CLIC4 was first found on the cell periphery, with gp135+/Rab11a+ apical vesicles, and then concentrated near the gp135-enriched AMIS juxtaposing Rab11a-labelled REs." (PMID 26786190, 2016).